EPCAM (epithelial cell adhesion molecule)
Diseases named in the same sentence as EPCAM in open-access papers (continued):
Sharing a sentence is not in itself a finding about the gene and the disease.
tumor (continued). "One of the tumor cell populations, CD45−CD56−(EpCAM+FOLR1+CD24+), demonstrated high expression of the markers." (PMID 37894472, 2023). "Several surface markers of CSCs have been identified, including EpCAM, CD44 and CD133, which provide a possible identification method of CSCs in the tumor stroma." (PMID 36810098, 2023). "First discovered as a tumour antigen in CRC, epithelial cell adhesion molecule (EpCAM) has been shown to down-regulate E-cadherin expression and/or its function in cancer cells, thereby promoting tumour spread." (PMID 37533952, 2023). "The other groups received tumor cells, Dual-RevCAR T-cells together with either RevTM CEA-IgG4-7B6, RevTM EpCAM-IgG1-5B9 or a combination of both RevTMs." (PMID 38169746, 2023). "EpCAM, a well-characterised human TAA has been shown to favour immune evasion by CRC tumour cells by adopting Th-2 responses in preference to Th-1 responses." (PMID 37533952, 2023). "Tumor markers (MUC1, EGFR, and EPCAM) are identified in CCA, and this marker combination is applied to detect tEVs in clinical bile samples." (PMID 36698298, 2023). "Enrichment with CSCs in the tumor spheres was confirmed by an increase in the CSC markers CD44, Nanog, EpCAM, and OCT4." (PMID 37300334, 2023). "In this study, the 3DISCO/iDISCO+ approach successfully cleared liver tissue while maintaining tissue integrity and allowed immunolabeling of intrahepatic vasculature and CRC tumor cell markers (MECA-32 and EpCAM, respectively)." (PMID 37077833, 2023). "According to the results, the administration of EpCAM-redirected CAR-Ts into mouse models reduced the size of the established tumors and remarkably slowed down tumor outgrowth in comparison with the control group." (PMID 38146364, 2023). "In detail, Mdivi-1 inhibits the self-renewal and tumor initiation capacities of CD133+CD15+ brain tumor-initiating cells (BTICs) and decreases the levels of stemness genes in EpCAM+CD133+ liver cancer stem cells (LCSCs)." (PMID 37370081, 2023). "The in vivo anti-tumor activity of Dual-RevCAR T-cells redirected via combination of anti-CEA and anti-EpCAM RevTMs was studied." (PMID 38169746, 2023). "Seventy-five percent of the tumours with TIL and 67% of cases with Crohn-like lymphocytic aggregates showed EpCAM overexpression (p < 0.025; p < 0.020, respectively)." (PMID 37533952, 2023). "Our study reveals a novel functional region of BAP31, and an intrabody against it inhibits N-glycosylation of EpCAM, activates genes related to cytotoxic autophagy, and inhibits the PI3K-Akt-mTOR pathway, significantly inhibiting tumor proliferation." (PMID 37834237, 2023). "RIP can trigger EpCAM-mediated signal transduction through the shedding of EpEX by ADAM17 and EpICD by γ-secretase complex and play important roles in tumor initiation and progression." (PMID 37543570, 2023). "Cell aggression was observed, indicating that compared with EpCAM mAb or CD3 mAb, T cells were significantly redirected to tumor cells by CD3×EpCAM BsAb." (PMID 35281893, 2022). "Blockade of PMPCB suppressed EpCAM expression and Wnt/β-catenin signaling, thus resulting in apoptosis of EpCAM+ HCC cells and tumor suppression." (PMID 36369033, 2022). "Moreover, HCC patients with high AFP serum levels (> 300 ng/mL) and positive staining for the epithelial cell adhesion molecule EpCAM show significantly higher microvessel density and tissue expression of vascular endothelial growth factor, which may be related to tumor angiogenesis." (PMID 36258212, 2022). "Tumor cells (CD45−, EPCAM+) in the MYC-OFF state displayed significantly more surface MHC-I protein than MYC-ON tumor cells." (PMID 35760778, 2022). "Accordingly, in this study, we aimed to characterize the expression of putative tumor markers including CD133 and EPCAM in blood circulating EVs of patients with metastatic CRC." (PMID 35267665, 2022).
tumor (continued). "The findings observed a significant direct correlation between EpCAM/CD166 phenotypes expression and tumor stage (P = 0.03), tumor differentiation (P = 0.05), neural, and lymph node invasion (P = 0.01)." (PMID 35016698, 2022). "In the presence of EpCAM expressing RB tumor cells, EpCAM×CD3 has potent anti-tumor activation in vitro via induction of interleukin and cytokine secretion by pre-activated lymphocytes." (PMID 36132125, 2022). "In the tumor with high EpCAM expression such as 4T1 and MC38-EpCAM models, VV-EpCAM BiTE exerted a more potent antitumor effect than VV-Ctrl." (PMID 36451817, 2022). "The expression levels of CSC markers, such as ALDH1A1, EpCAM, CD133, CD44V6, and CD44V8-10, were confirmed in the tumor tissues of patients with CCA using IHC staining." (PMID 35223723, 2022). "Epithelial cell adhesion molecules (EpCAM) CD133, EGFR, and HER2 are additional targets overexpressed in cancer cells, cancer stem cells, and/or tumor endothelial cells, which have been exploited in the design of aptamer-functionalized nanoparticles." (PMID 35626078, 2022). "The assay involves the use of membrane-bound antibodies against the epithelial cell adhesion molecule (EpCAM, or CD326) present on tumor cells and their subsequent culturing/expansion in both in vivo and in vivo conditions." (PMID 35303879, 2022). "The third-generation EpCAM-CAR-T cells were able to exhibit in vitro killing activity against OC cell line SKOV3, as well as significantly reduce the tumor size in OC xenograft mouse models." (PMID 35269636, 2022). "Despite a few limitations such as lack of overall survival and follow-up data, our results justify the importance of EpCAM separately and the connection between overexpression of two CSCs markers (EpCAM, CD166) and tumor aggressiveness in CRC tissues." (PMID 35016698, 2022). "As a result, tumor cells acquired platelet markers (CD61 and CD42), showed decreased EpCAM, expressed epithelial-to-mesenchymal transition markers, and increased proliferation rates." (PMID 35265204, 2022). "As a result, both MC38-EpCAM and MC38 cells elicited high levels of IFN-γ from splenocytes, in which MC38-EpCAM induced IFN-γ was even higher, indicating that the VV-EpCAM BiTE mediated immune responses in mice was specific to both MC38 tumor and EpCAM." (PMID 36451817, 2022). "Tumor cells in LNs showed cytoplasmic expression of PSA, PSCA, and AGR2; membrane and cytoplasmic expression of PSMA and EpCAM; and nuclear expression of NKX3-1." (PMID 36185585, 2022). "These can also be identified in circulation and paired tumour and peritumour tissue samples with the co-expression of CD45, CD14 and EpCAM markers." (PMID 35884505, 2022). "In order to verify the relationship between MAGE-A3 and tumor stemness regulation, we also detected the expression of tumor stem cell markers CD44 and EpCAM in these tissues." (PMID 36367777, 2022). "The expression levels of CSC markers, such as ALDH1A1, EpCAM, CD133, CD44V6, and CD44V8-10, were determined in the tumor tissues through IHC staining." (PMID 35223723, 2022). "Tumor cells (cluster 0, 2, 5, 6, 7, 8, 10, and 11) were distinguished by the expression of CD24, KRT19, and EPCAM." (PMID 36291687, 2022). "Our data showed that normal tissue-derived organoids exhibited some tumor-like features, so we explored the expression patterns of VIM and EPCAM in the epithelial cells from all patients." (PMID 35484598, 2022). "In non-small cell lung cancer (NSCLC) cell lines, the expression of E-cadherin, EpCAM and αvβ6 was found to induce the transcription of TGF-β1 and TGF-βR1 in normal fibroblasts to modulate tumor progression and therapeutic responsiveness." (PMID 36369033, 2022).
tumor (continued). "After incubation with CD3×EpCAM BsAb at 100 ng/ml, redirected T cells around tumor cells were observed, and CFSE+/PKH26+ cells were more efficiently assembled than CD3 mAb or EpCAM mAb groups." (PMID 35281893, 2022). "EPCAM and CD45 have been largely employed to enrich circulating tumor cells (CTCs), which showed prognostic potential in CRC." (PMID 35267665, 2022). "Tumor cell-macrophage hybrids express both macrophage (CD14, CD68, CD163, CD204, and CD206) and tumor-specific markers (ALCAM, MLANA, KRT, EpCAM, CXCR4, and CD44)." (PMID 35242760, 2022). "It has been previously demonstrated that colorectal CICs are enriched in tumor spheres or in freshly fractionated ALDH(+), or CD133(+), or EpCAM(+) cells." (PMID 35982950, 2022). "Oportuzumab monatox is comprised of an anti-EpCAM single-chain variable fragment and a fragment of pseudomonas exotoxin A (ETA), which displays anti-tumor effects after the ADC is internalized and ETA is released." (PMID 36369033, 2022). "The tumor lesions identified grossly were confirmed to have tumorigenic origins by flow cytometric identification of EpCAM+ and CD45+ cell populations in the excised tumor lesions single cell suspensions." (PMID 35892161, 2022). "EpCAM-positive HCC cells display stem cell-like properties, which promote tumor formation and proliferation." (PMID 35154157, 2022). "Therefore, EpCAM immunostaining combined with tissue/cell morphology features could clearly distinguish the two types of liver parenchymal cells in paratumor tissues and the three types of parenchymal cells in tumor tissues." (PMID 35223840, 2022). "Some specific markers on the surface of various cancer cells, such as epithelial cell adhesion molecule (EpCAM) and type I transmembrane glycoprotein CD44, can be used for cell membrane targeting in tumor PDIT." (PMID 35910806, 2022). "LCSL cells express liver stem cell markers, including epithelial cell adhesion molecule (EpCAM), cytokeratin 19 (CK19), OV6 and Sal-like protein 4 (SALL4), and account for approximately 10% of the overall tumor tissues." (PMID 35223840, 2022). "Epithelial cell adhesion molecule (EPCAM) is a transmembrane glycoprotein expressed on the surface of most epithelial and epithelium-derived tumor cells and reported to regulate stability of epithelial tight junction proteins, claudins." (PMID 35730316, 2022). "Solitomab or MT-110 is a BiTE against EPCAM and CD3, which bridges between tumor cells and T cells, leading to lysis of tumor cells." (PMID 35986321, 2022). "Some well-known marker genes were used to identify cell types, such as EPCAM and KRT19 for tumor cell, COL1A1 and ACTA2 for CAF, CD3D and CD3E for T cell, and CD68 and CD14 for macrophage." (PMID 36499343, 2022). "BMP4 and EPCAM are involved in inducing epithelial-mesenchymal transition (EMT) and promoting tumor cell migration of ESCA." (PMID 35069736, 2022). "Gene expression profiles of the high-risk group correlated positively with the upregulation of CSC markers, CD24, CD44, CD20, FOXM1, and EpCAM, and significant enrichment of other ESC signatures, indicating that these were tumor-promoting targets." (PMID 35814473, 2022). "We anticipate that the majority of CTCs is detected using EpCAM and EGFR as tumor markers, combined with morphological confirmation." (PMID 36613466, 2022). "Cotreated with regorafenib improves EpCAM CAR NK-92 cells by enhancing immune cell infiltration, downregulating immune suppressive cell subsets and improving tumor vasculature." (PMID 36369033, 2022). "UMAP analysis further revealed heterogenic distribution of three liver CSC‐like markers (PROM1, EPCAM, and CD44) within tumor organoids." (PMID 34105295, 2021). "This proximity ligation approach was additionally verified for the sensitive detection of tumour-derived exosomal PD-L1/CD63, and exosomal CD63/EpCAM/MUC1 using multiple fluorophore coded aptamers." (PMID 34855021, 2021).
tumor (continued). "Tumor stroma (fibronectin) in red, tumor cells (EpCAM in EGI-1, MMTV-PyMT, and KPC tumor models, CD44 in mPDAC tumor models), in blue and T cells (CD8 in mPDAC and KPC, Calcein in MMTV-PyMT, and EGI-1 tumor models) in green." (PMID 34106045, 2021). "The concordance rate between ESR1,PR, HER2 expression on EpCAM(+) CTC fractions and the primary tumor was 27.9%, 34.9% and 65.1% respectively." (PMID 33799422, 2021). "Collectively, our results indicated a better clinical significance of tumor-specific markers (CEA and HE4 mRNAs) compared to epithelial-specific markers (EPCAM and MUC1 mRNAs)." (PMID 34006887, 2021). "Tumor-derived single-cell suspension was stained with antibodies against CD45, CD31, EpCAM, and AXL." (PMID 34254585, 2021). "These candidate markers (CLDN4, EPCAM, CD151, LGALS3BP, HIST2H2BE, and HIST2H2BF) effectively isolated tumor-derived EVs in clinical samples." (PMID 34948417, 2021). "In conclusion, this is the first study evaluating a multi-marker panel of mRNAs, including tumor cell-specific (CEA, CA125 and HE4) and epithelial-specific (EPCAM and MUC1) mRNAs in EOC patients before and after adjuvant chemotherapy." (PMID 34006887, 2021). "The detection and analysis of CTC markers (EpCAM and CK8, 18, CD45 Vimentin,Twist and 19) and CSCs markers (NANOG) are of great value in the evaluation of tumor progression." (PMID 34123777, 2021). "Consistently, restoration of EpCAM and Sox9 expression in JMJD2D-knockdown LCSCs partially rescued the subcutaneous tumor growth." (PMID 33434575, 2021). "It was also demonstrated that sEVs derived from ascites of OCs have potential as diagnostics, because they express tumor-intrinsic biomarkers, such as CD24 and EpCAM." (PMID 34571921, 2021). "Promising tumor targets include carcinoembryonic antigen (CEA), epithelial cell adhesion molecule (EpCAM), integrin αvβ6, and urokinase-type plasminogen activator receptor (uPAR)." (PMID 33799475, 2021). "Through bioinformatics software, it was found that the tumor stem cell markers CD44 and EpCAM promoter had MKL-1 binding site CArG box." (PMID 34239355, 2021). "The authors designed a bispecific RNA–aptamer chimera able to target two tumor markers, CD44 and epithelial cell adhesion molecules (EpCAM), combined through a double-stranded RNA adaptor." (PMID 34884745, 2021). "Human Differentiated Protein 133 (CD133), EpCAM, CD44, and CD90 are known as representative markers of a CSC state in various tumor tissues, including HCC." (PMID 34671766, 2021). "Our data support the use of the epithelial marker EPCAM for CTC isolation and enumeration, as its expression level was unchanged in tumour cells in all four PDX models despite significant shifts in expression of many other genes." (PMID 34206049, 2021). "Comparisons of CTC detection with EpCAM compared to multiple surface markers (EGFR, HER2 and PSMA) was evaluated and correlated with the tumor size." (PMID 34600526, 2021). "As previously discussed, EpCAM and CTSL are both secreted into the extracellular space where they likely come in contact in the tumor microenvironment." (PMID 33980181, 2021). "The coating of the magnetic nanoparticles consist of antibodies such as epithelial cell adhesion molecule (EpCAM) and CD52 as markers to attempt to remove tumor cells from the blood." (PMID 34067587, 2021). "Comparison of the frequency and number of tumor cells in the primary tumor and among CTCs was carried out by detecting of the co-expression of CK7, EpCAM, and N-cadherin in the same cell." (PMID 33801519, 2021). "By contrast, recipient animals that received CD8+ CMV-specific T cells and EpCAM-MC APEC exhibited significant decreases in EpCAM+/GFP+ cells over time, while EpCAM−/mCherry+ tumor cell number was largely unaffected." (PMID 34415995, 2021).
tumor (continued). "Total RNA and protein of the mouse tumor tissues were extracted, and the expression of CD44, EpCAM, and MKL-1 was detected by RT-PCR and Western Blot, respectively." (PMID 34239355, 2021). "Several studies using CAR-T cells targeting CEA or EpCAM showed that co-inoculation of CAR-T and tumour cells inhibited or delayed tumour formation." (PMID 34769211, 2021). "The volumes of tumors in the EpCAM CAR T group remained low, showing stronger suppression of tumor growth than in the control T group." (PMID 34790117, 2021). "Conventionally, the detection of CTC linked to PDA is based on the methodologies including density centrifugation and RT-PCR detection of tumor markers CEA, cytokeratin 20, or EpCAM." (PMID 33593396, 2021). "EPCAM and COL1A1 were used to identify tumor epithelial cells and fibroblasts, as described in a previous study." (PMID 34771607, 2021). "The results showed that compared with the tumor tissues in vivo, the tumor tissues have more expression of CD44 and EpCAM." (PMID 34239355, 2021). "In accord with previous results for the specific tumor-killing effect of EpCAM-CAR T cells alone in vivo, the volumes of tumors in the EpCAM CAR T group increased significantly slower than those in the mGFP CAR T group." (PMID 34790117, 2021). "CEA, EpCAM, αvβ6, and uPAR expressions were low (TIS < 6) in the tumor bed in, respectively, 93%, 95%, 85%, and 62.5% of cases." (PMID 33799475, 2021). "The next best targets are overexpressed proteins on tumor cells compared to healthy cells, which is the case for most of the clinically targeted TAAs, such as CEA, EGFR, EpCAM and HER2." (PMID 33466732, 2021). "Recently, combined treatment of a CRC mouse model with epithelial cell adhesion molecule (EpCAM)-CAR-NK-92 and regorafenib (a sorafenib-related multikinase inhibitor) achieved a synergistic tumor suppression than either treatment alone." (PMID 34557197, 2021). "In this study, we combined EpCAM/CD3 BsAb and MUC-1/CD3 BsAb to target both EpCAM and MUC-1 on the surface of tumor cells." (PMID 34522164, 2021). "As such, tumor heterogeneity, especially with regards to the diversity, density and steric complementarity of cell surface adhesion molecules (e.g., TF antigen, Cadherins, galectin-3, EpCAM, Na+/K+-ATPase, and glycoprotein 100, etc.)may prove to be extremely difficult to address in the clinic." (PMID 34070233, 2021). "A panel of tumor-derived extracellular vesicle markers, including EGFR, EPCAM, HER2, MUC, GPC1, WNT2, and GRP94, was investigated." (PMID 33803470, 2021). "EpCAM CAR NK-92 cells combined with a tumor kinase inhibitor (e.g., Regorafenib) achieved significant anti-tumor responses in human colorectal cancer xenografts." (PMID 34943898, 2021). "Cancer-associated mutations that prevent EpCAM cell surface expression abrogate the ability of EpCAM to inhibit CTSL activity and tumor cell invasion." (PMID 33980181, 2021). "We first evaluated the feasibility of co-targeting HER2 and EpCAM in SKOV3 cells, studied binding, internalization, and cytotoxicity of Ec1-LoPE in vitro, and biodistribution and specificity of tumor targeting in vivo." (PMID 34439094, 2021). "Median TIS in the tumor bed and adjacent pre-existent mucosa was respectively 0 (range 0–12) and 9 (range 0–12) for CEA, 0 (range 0–12) and 12 (range 0–12) for EpCAM, 0 (range 0–12) and 6 (range 0–12) for αvβ6, and 3.5 (range 0–12) and 1 (range 0–12) for uPAR." (PMID 33799475, 2021). "For example, a single tube liquid biopsy allowing simultaneous analysis of cfDNA, tumor-derived extracellular vesicles and CTC with high and low EpCAM expression proved to be useful in predicting survival among advanced NSCLC." (PMID 33937034, 2021).